CGAS (cyclic GMP-AMP synthase)
Diseases named in the same sentence as CGAS in open-access papers (continued):
Sharing a sentence is not in itself a finding about the gene and the disease.
cancer (continued). "The cytosolic nucleic acid sensors cyclic GMP-AMP synthase (cGAS) and retinoic acid inducible gene I (RIG-I) are not only important for detection of infected cells but also for immune recognition of cancer cells." (PMID 34733287, 2021). "Three categories of cancer cells—cells with high cGAS and SQSTM1 (786-0 and PC3M), low cGAS and SQSTM1 (HeLa and HCT116), and high SQSTM1 but low cGAS (DU145)—were selected." (PMID 34123836, 2021). "For instance, chromosomal DNA-rich sEVs from cancer cells treated with topotecan activated DCs via the cGAS-STING signaling pathway, thereby inducing cancer cell apoptosis and inhibiting tumor progression." (PMID 33791224, 2021). "The cGAS-STING pathway is activated by double-stranded DNA in the cytoplasm and is well known for its importance in antiviral response, inflammation and cancer." (PMID 34341449, 2021). "Recent evidence indicated that cyclic GMP-AMP synthase (cGAS)/stimulator of IFN genes (STING) signaling is important for the induction of type 1 IFN and plays an important role in cancer immunity." (PMID 34768716, 2021). "We expose the role of the cGAS/STING pathway in inflammatory diseases, neurodegenerative conditions and cancer." (PMID 34659260, 2021). "Chromosome instability (CIN) can induce chronic inflammatory signal transduction by continuously activating cGAS/STING signaling and the downstream NF-κB pathway, resulting in the increased migration and invasion of cancer cells." (PMID 35046953, 2021). "In the current study, we discovered the high expression of cGAS in GC tissues and 26 GC cell lines, suggesting inactivation of the cGAS in GC due to the high chromosomal instability (CIN), which produces a large amount of cytoplasmic dsDNA in cancer cells." (PMID 37305397, 2021). "The activation of the cGAS-STING signaling pathway in DCs is a central step of the whole cancer-immunity cycle, which can be initiated by phagocytosis of dead or damaged cancer cells, exosome transfer, and cGAMP gap junctions." (PMID 34483930, 2021). "The cGAS/STING pathway was also shown to be a possible therapeutic target in the inflammatory microenvironment and cancer." (PMID 34768716, 2021). "Suppression of micronuclei formation and the cGAS-STING pathway significantly delays metastasis even in the aneuploid cells, indicating that micronuclei increase the malignant transformation of the cancer cells." (PMID 34526560, 2021). "Knockdown of cGAS along with induction of mitotic arrest in HeLa and U2OS cancer cells clearly resulted in an increase of micronuclei formation and chromosome mis-segregation." (PMID 34948027, 2021). "Still, it can promote the cGAS-STING pathway only in mice, which cannot be a functional treatment for cancer patients." (PMID 34858438, 2021). "Meanwhile, the combination of the cGAS-STING signal pathway agonists and different cancer treatments (radiotherapy, chemotherapy) is also a promising option." (PMID 34956229, 2021). "Despite these data, several findings showed that triggering the cGAS-STING pathway regulates cellular senescence and apoptosis and enhances adaptive anti-cancer immunity." (PMID 34072037, 2021). "The comprehensive elucidation of the interplay between the caspase family and the cGAS‒STING signaling pathway will be useful in identifying novel therapeutic targets and potential therapies against infectious diseases and cancer." (PMID 34718659, 2021). "Growing tumors produce IFNs as a result of activation of the cGAS-STING pathway, which is further augmented by cancer therapies." (PMID 33547304, 2021). "The cGAS-STING pathway has been shown to be a key signaling pathway in antitumor immunity and cancer therapeutics." (PMID 34712244, 2021). "Signaling through cGAS, a protein that detects DNA in the cytosol, prevents chromosome instability (CIN) in cancer cells by regulating the levels of the cell-cycle inhibitor p21." (PMID 32284536, 2020).
cancer (continued). "Although one study reported that cGAS and STING were highly expressed in various cancer tissues using bioinformatics analysis, their expression remains to be confirmed in more cell lines." (PMID 33490069, 2020). "The cGAS-STING, TBK1, and IRF3 increasingly express in pan-cancer cells, and their gene expression level negatively correlates with their methylation in most cancer types." (PMID 33643304, 2020). "Beyond the well-known role of the cGAS-STING pathway in combating pathogens, recent studies have also revealed the role of this pathway in cancer." (PMID 32532954, 2020). "In this field, with particular regard to DNA-based viruses (i.e., HSV-1), antiviral activity of the cGAS/STING axis represents the main hurdle for viral spread and cancer cell killing." (PMID 33213060, 2020). "T-MPs present DNA fragments from cancer cells for APC, stimulating the production of type I IFNs by the activation of the cGAS-STING pathway." (PMID 32887628, 2020). "For example, cancer cell chromosomal instability promotes cytosolic DNA leakage by activating the cGAS‐STING pathway response and promoting an inflammatory microenvironment that increases the occurrence of cancer metastasis." (PMID 34766117, 2020). "For instance, the cGAS–STING axis plays a role in activating a sterile cellular stress response, such as that occurring in cancer cells due to chromosomal abnormality, genomic DNA damage, and hyperproliferation." (PMID 32316236, 2020). "Although the application of STING agonists is exciting, the recent correlation between the cGAS-STING pathway and metastasis also suggests the prospect for STING inhibition in late-stage cancers." (PMID 32571374, 2020). "Here, we review the antitumor roles of the cGAS-STING pathway during tumorigenesis, cancer immune surveillance, and cancer therapies." (PMID 32541866, 2020). "cGAS-STING pathway interplays with other innate immune pathways, by which it participates in regulating infection, inflammatory disease, and cancer." (PMID 32411126, 2020). "Because of the importance of the cGAS-STING pathway in antitumor activities, cyclic dinucleotide (CDN), a STING agonist structurally related to cGAMP, is thought to be useful for anti-cancer therapy." (PMID 33633744, 2020). "Cyclic GMP–AMP (cGAMP) synthase (cGAS) and stimulator of interferon (IFN) gene (STING) were reported to play important roles in anti-cancer immunity, e.g. T cell immunity." (PMID 33268765, 2020). "Current researchers have found correlations between the cGAS-STING pathway and those cancer vaccines." (PMID 32887628, 2020). "The integrity of the cGAS-STING pathway is critical for response to the invasion from multiple pathogens and tumors, while cancers including melanoma and colon cancers are common with its deficiency." (PMID 32571374, 2020). "Stimulated by cytosolic DNA, active cyclic GMP-AMP synthase-stimulator of interferon genes (cGAS-STING) pathway stimulates the expression of type I interferon (IFN) in cancer cells or DCs, initiating innate anti-cancer immunity." (PMID 30935414, 2019). "In this review, we highlight the latest understanding and the advances of cGAS-STING-targeting strategies, especially in combination with immunotherapies such as cancer vaccine, ICI, oncolytic virus, and chimeric antigen receptor T cell (CAR-T) therapy." (PMID 30935414, 2019). "The frequent activation of cGAS and/or STING signaling in cancer strongly suggests an oncogenic role for this pathway." (PMID 31658669, 2019). "Activated cGAS-STING pathway and its downstream signals boost the whole cancer-immunity cycle by enhancing cross-presentation and immune-killing activity." (PMID 30935414, 2019).
cancer (continued). "cGAS and its downstream target STING are believed to form an essential node between cancer cells and the immune microenvironment, as CIN often coincides with cytosolic DNA." (PMID 31658669, 2019). "Given the widespread nature of CIN in human cancer, therapies targeting CIN and cGAS/STING have therapeutic potential to reduce therapy resistance and reduce metastasis." (PMID 31681587, 2019). "As a versatile pathway, the role of cGAS-STING needs further investigation especially considering that its function changes along with agonist dose, cancer type, and disease stage." (PMID 30935414, 2019). "Indeed, it has been indicated that the cGAS-STING pathway could promote cancer formation." (PMID 31114634, 2019). "In this minireview, we discuss how cGAS–STING and RIG-I–MAVS pathways have been targeted for cancer treatment in preclinical translational researches." (PMID 29686682, 2018). "The cGAS/STING pathway has been targeted in the clinic to induce both innate immune response and subsequent adaptive immune response for cancer treatment." (PMID 30080846, 2018). "Further work will help identify the cGAS-dependent or -independent functions of TRIM56 in host antimicrobial immunity and cancer." (PMID 29426904, 2018). "Altogether, these results indicate that cancer cell-intrinsic activation of type-I IFN pathway is required for optimal in situ vaccination by radiation and anti-CTLA4, and is mediated via cGAS-STING." (PMID 28598415, 2017). "Consequently, the cGAS-STING signaling pathway is involved in a variety of diseases, including infections, autoimmune disorders, cancers, fibrosis, and neurodegenerative conditions." (PMID 41487469, 2026). "Collectively, our findings identify cGAS-STING not only as a therapeutic target but also as a predictive biomarker of immunotherapy responsiveness, supporting a novel epigenetic–immune combination strategy for cancer treatment." (PMID 40830678, 2026). "Because cGAS senses DNA in a sequence-independent manner, we propose that this presents a general strategy for targeting all ecDNA species regardless of cancer type." (PMID 41509453, 2026). "Chronic activation of the cGAS-STING pathway in cancer cells enhances non-canonical NF-κB signaling, which facilitates metastasis." (PMID 40770563, 2026). "This article highlights some promising therapeutic avenues that leverage the interplay between cGAS-STING and ferroptosis using nanomedicine, which could be used to treat cancer." (PMID 40846966, 2025). "However, it activates the cGAS-STING pathway only in mice, making it unsuitable for human cancer treatment." (PMID 40520004, 2025). "The cGAS-STING axis is vital for tissue homeostasis and host defense, while dysfunction of cGAS-STING activates pro-inflammatory signaling pathways, leading to inflammatory, autoimmune, degenerative diseases, and cancer." (PMID 40552295, 2025). "Recent preclinical research, including in vitro and in vivo studies, have expanded our understanding of the molecular mechanisms by which cancer cells autonomously and non-autonomously evade cGAS-STING activation." (PMID 40846966, 2025). "Dysregulation of the cGAS-STING pathway plays a pathophysiological role in spectrum of human inflammatory diseases, neurodegenerative disease, liver disease, infectious diseases and cancer." (PMID 39999142, 2025). "cGAS-STING pathway modulators are new and attractive targets for targeted medicine against cancers." (PMID 40552295, 2025). "Ultimately, overcoming the obstacles that tumors pose to the cGAS-STING pathway could lead to more effective and targeted cancer therapies." (PMID 40739089, 2025). "These nucleic acids are responsible for the activation of the cyclic GMP-AMP synthase - stimulator of interferon genes (cGAS/STING) pathway, regulating the immune response through the transcription of type I interferon, favoring immunogenicity in cancer cells." (PMID 40943463, 2025).
cancer (continued). "We also review the role of the interplay between cGAS-STING and ferroptosis in cancer genesis." (PMID 40846966, 2025). "Furthermore, we also provide an up-to-date insight of LLPS in driving the immune signaling pathway, including those triggered by TCR, BCR, cGAS-STING, and RIG-1 in cancer." (PMID 40104511, 2025). "Since the cGAS-STING pathway is pivotal in cancer immune surveillance, IRF4 may also play a role in the evasion of the cGAS-STING-mediated innate immune response in EBV latency, at least by regulating their expression." (PMID 40733503, 2025). "On the one hand, the cGAS-STING pathway plays a vital role in antitumor immunity and may be an attractive anti-cancer immunotherapeutic drug target." (PMID 39975558, 2025). "However, the potency of this response can be limited in tumors with intrinsic suppression of the cGAS-STING pathway, a phenomenon recently documented in specific cancer subtypes." (PMID 41295487, 2025). "Moreover, the activation of the cGAS-STING pathway has a dual role, promoting both cancer progression and innate immunity." (PMID 40986050, 2025). "Additionally, MOMP caused by BAX/BAK can lead to the release of mtDNA and mt-dsRNA into the cytosol, activating the cGAS/STING and RIG-I/MAVS pathways within cancer cells, which elicits the secretion of type I IFN cytokines for ICD induction." (PMID 41304887, 2025). "cGAS-STING and autophagy have been shown to be interplayed, which may influence the progression of cancer." (PMID 40552295, 2025). "In addition, chromosomally unstable cancer cells increase the expression of IL6 and trigger IL6 signaling downstream through the cGAS-STING pathway, thereby promoting cancer cell survival and growth." (PMID 39744421, 2025). "Then, we review the role of the interplay between cGAS-STING and ferroptosis in cancer genesis." (PMID 40846966, 2025). "This article highlights some promising therapeutic avenues that leverage the interplay of cGAS-STING and ferroptosis by nanomedicine, which could be used to treat cancer." (PMID 40846966, 2025). "The cGAS-STING pathway plays a crucial role in cancer therapy, not only as a therapeutic target but also as a key mediator activated during various therapeutic interventions." (PMID 40052963, 2025). "cGAS is a multifunctional cytoplasmic DNA sensor that binds endogenous or pathogen-derived dsDNA and induces the expression of IFN, a key event in regulating cellular senescence, autophagy, cancer development and viral defense." (PMID 39747662, 2025). "Collectively, these results indicate that Nb289‐OMVs alone can initiate the activation of the cGAS/STING/IFN‐I axis, which may result in ICD induction in cancer cells." (PMID 40240911, 2025). "cGAS is a pivotal DNA sensor in the innate immune pathway, detecting abnormal cytosolic DNAs and activating IFN-I via the stimulator of interferon genes (STING) in both cancer and immune cells." (PMID 40282455, 2025). "This is consistent with other studies showing that the cGAS–STING pathway is widely active in senescent cells, further confirming the importance of this pathway in regulating cellular inflammatory response and cancer progression." (PMID 40227735, 2025). "However, recent studies have revealed that the cGAS-STING pathway can also contribute to chronic inflammation and tissue damage in various pathological conditions, such as autoimmune diseases, cancer, and neurodegeneration." (PMID 39149145, 2024). "In most cases, autophagy negatively regulates cGAS-STING signaling and may therefore negatively impact cancer therapy." (PMID 38660307, 2024). "In this regard, the relationship between the cGAS/STING axis and senescence can be viewed as an example of the complex crosstalk between senescence induction and anti-cancer immune response taking into consideration its contribution to cancer “immunoediting”." (PMID 38561826, 2024).
cancer (continued). "Also, cGAS-dependent IL-6 secretion and IL6R signaling have recently been demonstrated to provide pro-survival signals in cancer cells, including TNBCs59." (PMID 38167507, 2024). "Recent findings have shown that activation of the cyclic GMP‐AMP synthase‐stimulator of interferon genes (cGAS‐STING) pathway can enhance natural immunity and increase lymphocyte infiltration into the TME, which presents a promising strategy for cancer immunotherapy." (PMID 38193125, 2024). "Besides the cGAS/STING pathway, other immunomodulatory mechanisms involved in cancer include Toll-like receptor (TLRs), RIG-I, NLRP3, and CD47-SIRPα pathways." (PMID 39318624, 2024). "Moreover, the interplay between cGAS-STING and cancer is intricate, encompassing functions in immune suppression as well as facilitation of metastasis." (PMID 39420203, 2024). "Finally, further efforts in understanding cGAS-STING signaling and autophagy pathways individually as well as their interactions will be instrumental for their targeting in cancer." (PMID 38660307, 2024). "This groundbreaking study introduces the first small molecule-based photoactivators that can both activate the cGAS-STING pathway and induce pyroptosis, offering a novel strategy for cancer immunotherapy that leverages both pathways to combat tumor growth effectively." (PMID 39221221, 2024). "The importance of the cGAS-STING pathway for inflammation and immunity, coupled with checkpoint inhibitors, cytokine therapeutics, and cell-based therapies, underscore the compelling rationale for targeting this pathway in cancer immunotherapy." (PMID 38999073, 2024). "The CGAS-STING axis is composed of cyclic-GMP-AMP synthase (cGAS) and cyclic GMP-AMP receptor stimulator of interferon genes (STING), and plays an important role in a variety of diseases, including malignant tumors, DNA damage, and inflammation-related diseases." (PMID 38643466, 2024). "In conclusion, the combination of photothermal, photodynamic and sonodynamic therapeutic methods with cGAS-STING agonists could offer more precise and safe approaches with broad future prospects for cancer therapy." (PMID 39125107, 2024). "It has also been shown that IR leads to cyclic GMP-AMP synthase (cGAS) activation, a stimulator of the interferon gene (STING) pathway, leading to the production of proinflammatory signals that have a bearing on the fate of cancer cells and tumors." (PMID 39044839, 2024). "We will provide an overview of the involvement of cGAS-STING signaling and autophagy in cancer progression and treatment strategies individually, as well as their interactions in the context of cancer and how this might affect potential therapeutic strategies." (PMID 38660307, 2024). "The fact that cytosolic DNA can activate the NF-κB cascade without initiating type I IFN indicates that downstream alterations of cGAS/STING signaling are preferred and might favor cancer cells." (PMID 39544936, 2024). "The article concludes with the addition of cGLRs in the PRR family and (cGAS/STING signaling) ideas of how to leverage them to revolutionize the field of vaccinology and immunotherapeutics for cancer and infectious diseases via cross-talking with other PRR family members." (PMID 38339107, 2024). "Interestingly, some highly invasive tumors seem to rely on the cGAS-STING pathway to facilitate tumorigenesis, impacting cancer treatment approaches." (PMID 38545114, 2024). "Interestingly, direct coculture experiments revealed that cGAS-STING activation in cancer cells was necessary for TDDC activation, raising questions about the interplay between exosomal DNA and the cGAS-STING pathway." (PMID 39449023, 2024).